SRSF1 (serine and arginine rich splicing factor 1)
Diseases named in the same sentence as SRSF1 in open-access papers (continued):
Sharing a sentence is not in itself a finding about the gene and the disease.
prostate carcinoma (18 papers, 2015 to 2025). A carcinoma that arises from epithelial cells of the prostate gland. "Copy number loss of 17q22 is correlated with lower RNF43 and SRSF1 expression, enzalutamide resistance, and poor prognosis in prostate cancer." (PMID 37848933, 2023). "Recently, the expression of specific proteins during immunohistochemical analysis such as serine/arginine splicing factor 1 (SRSF-1) or microvascular density (MVD) has also been reported to be associated with a worse prognosis in prostate cancer patients." (PMID 35159007, 2022). "A further important kinase that might impact on prostate cancer pathology is aurora A, which affects the production of ARv splice variants, likely also through control of SRSF1." (PMID 28382513, 2017). "SNHG7 contributes to the development of prostate cancer by promoting glycolysis via the SRSF1/c-Myc axis in two prostate cancer cell lines, PC-3 and DU-145." (PMID 40129567, 2025). "Concurrently, SRSF1 was relevant to prostate cancer and small cell lung cancer, which indicated its functions in promoting the progression of cancer." (PMID 38735973, 2024). "Tumor suppressor miR-30c is known to inhibit prostate cancer by targeting the 3′-UTR of the SRSF1 splicing factor oncoprotein to downregulate its expression in prostate cancer." (PMID 37705830, 2023). "The immunohistochemical expression of SRSF1 also correlated with a poor prognosis in adult diffuse gliomas, as well as with an increased cell proliferation in prostate cancer." (PMID 35056447, 2022). "Recently, our research group also reported the poor prognostic role of SRSF1 in adult diffuse gliomas, prostate cancer, and mesotheliomas." (PMID 35056447, 2022). "Meanwhile, it was reported that SRSF1 regulates splicing of AR pre-mRNA to generate AR-V7 in prostate cancer." (PMID 32106418, 2020). "Either SRPK1 siRNA knockdown or treatment by SPHINX and SRPIN340 inhibitors reduced the SRSF1, SRSF2 and SRSF5 phosphorylation causing increased production of the anti-apoptotic VEGF165b isoform in PC-3 prostate cancer cell line." (PMID 32596243, 2020). "Moreover, SRSF1 regulates the production of cyclin D1 (CCND1) isoform CCND1b in prostate cancer." (PMID 32106418, 2020). "A similar regulatory mechanism is also observed in prostate cancer, where selective upregulation of proangiogenic VEGF is under the direct control of SRPK1-regulated SRSF1 activity." (PMID 26273627, 2015). "on prostate cancer revealed that METTL3 promotes the stability of lncRNA SNHG7 through an m6A modification, and this stable lncRNA accelerates glycolysis in prostate cancer through the SRSF1/c-Myc axis." (PMID 39759516, 2024). "Notably, two SFs that are often upregulated in cancer cells, SRSF1 and SAM68, promote cyclin D1b splicing in prostate cancer cells." (PMID 26273627, 2015). "In addition to SRSF1, the roles of SRSF5 in breast and prostate cancers have been reported." (PMID 32106418, 2020). "SRPK1 inhibition keeps SRSF1 in the cytoplasm and, as a result, decreases the ability of the prostate cancer cell line PC-3 to form tumours in mouse xenografts, probably through changed patterns of VEGF mRNA splicing depriving prostate cancer cells from developing a blood supply." (PMID 28382513, 2017). "In the present study, we aimed to explore the relationships between the expression of certain genes (CYP7B1, SRSF-1, FAS, PSMA, ACC-1, CPT1a, and SREBP) and oncological factors in prostate cancer patients with and without diabetes." (PMID 38731981, 2024).
colon carcinoma (16 papers, 2010 to 2025). "Importantly, the β-catenin accumulation induced by either Wnt ligand stimulation or mutation of APC/β-catenin in colon cancer cells is dependent on SRSF1 and SRSF9." (PMID 23592547, 2013). "Together, these data suggest that SRSF1 directly controls tumour cell invasion and maintenance of stem cell properties in late-stage colon cancer." (PMID 35589755, 2022). "Recently SRSF1 is found to regulate the alternative splicing of the serine-threonine kinase DBF4B that plays a vital role in promoting tumorigenesis in colon cancer cells." (PMID 35027535, 2022). "Together with the findings from xenografts, we concluded that PP1α can attenuates colon cancer progression at least partially via antagonizing SRPK1/2-induced SRSF1 phosphorylation and downstream MKNK2a-MKNK2b splicing shift." (PMID 33602301, 2021). "SRSF1 targets are context-dependent with different substrates identified across breast, lung and colon cancer." (PMID 32599686, 2020). "Interestingly the presence of an alternative retained intron in the 3′UTR of splicing factor SRSF1 (ASF/SF2) protected this isoform from NMD degradation in HCT116 colon cancer cells." (PMID 34829789, 2021). "Six genes (aldehyde dehydrogenase 2, neural precursor cell expressed, developmentally down-regulated 9, filamin A, lamin B receptor, twinfilin actin binding protein 1, serine and arginine rich splicing factor 1) were closely related to the OS of colon cancer patients." (PMID 30155352, 2018). "To ascertain how SRSF1 levels correlate with human CRC progression, we analysed colon cancer tissue microarrays (TMAs) containing varying severities of the disease." (PMID 35589755, 2022). "AS-NMD of SRSF1, which involves an intron in the 3′UTR region of the gene, decreases mRNA stability and SRSF1 protein levels and, notably, it is altered in colon cancer." (PMID 24285959, 2013). "To directly demonstrate that SR proteins participated in β-catenin synthesis, we knocked-down SRSF1 or SRSF9 in RKO cells, a human colon cancer cell line in which Wnt signalling is relatively low." (PMID 23592547, 2013). "Colon cancer has also been found to activate the similar mechanism for Sam68, which binds phosphorylated Sam68 to the 3’ untranslated region (3’UTR) of the SRSF1 transcript and facilitates intron inclusion, which is necessary for the synthesis of full-length SRSF1 transcripts." (PMID 40032844, 2025).
cervical carcinoma (15 papers, 2013 to 2025). A carcinoma arising from either the exocervical squamous epithelium or the endocervical glandular epithelium. "For example, by binding to SRSF1, MIR155HG in DElncRNA enhances the inhibitory effect on SRSF1 to slow down the cervical cancer progression." (PMID 40129567, 2025). "miRNA-802 can modulate serine/arginine-rich splicing factor 1 (SRSF1) to inhibit cervical carcinoma cell proliferation and promote cell death." (PMID 37854681, 2023). "Other lncRNAs, such as MIR205HG, promote cervical cancer progression by targeting SRSF1 and regulating KRT17." (PMID 36144454, 2022). "A previous study reported that MIR205HG inhibits progression of cervical cancer by interacting with SRSF1 and modulating KRT17 expression." (PMID 33535182, 2021). "Additionally, a significant increase in SRSF1 levels was observed in cervical cancer cells, revealing a correlation between the increased cytoplasmic levels of SRSF1 and early tumor progression." (PMID 39286028, 2024). "For example, Metastasis-associated lung adenocarcinoma transcript 1 (MALAT1), which is excessively expressed in cancer tissues and cervical cancer cells infected with “high risk” HPV, interacts with several serine-arginine proteins, namely SRSF1, SRSF2, SRSF3 and SRSF5." (PMID 36144454, 2022). "Likewise, studies have shown that MIR205HG functioned as an oncogene in esophageal cancer, cervical cancer and head & neck squamous cell carcinoma by interacting with miR-214, SRSF1 and miR-590-3p, respectively." (PMID 33949284, 2021). "Furthermore, MIR205HG could also target SRSF1 and modulate KRT17 to mediate biological activities of cervical cancer cells." (PMID 34926294, 2021). "The serine/arginine-rich splicing factor 1, 2 and 3 (SRSF1, 2 and 3) are augmented in HPV16 positive cervical cancer cell lines compared with HPV16 positive non-tumorigenic cells." (PMID 29346309, 2018).
colorectal cancer (14 papers, 2015 to 2024). A primary or metastatic malignant neoplasm that affects the colon or rectum. "A previous study in colorectal cancer cells revealed that reducing SRPK1 levels by drug or siRNA treatment caused SRSF1 to be degraded in the cytoplasm." (PMID 32182205, 2020). "SRSF1 has been implicated in the alternative splicing of SLC39A14 in colorectal cancer cells." (PMID 36062189, 2022). "It has also been implicated in epithelial–mesenchymal transition (EMT) through the miR-468-3p/SRSF1 axis in colorectal cancer." (PMID 39001552, 2024). "In this study, the authors demonstrate that the SRSF1 splicing factor is essential to sustain the stem cell phenotype of WNT-activated colorectal cancers." (PMID 35589755, 2022). "Although no role for linear PABPN1 species in cancer has yet been reported, a circular RNA deriving from this locus has been reported to enhance colorectal cancer development by attenuating the activity of the splicing factor SRSF1 via the miR-638 axis." (PMID 36033512, 2022). "We next examined SRSF1 expression in different tumour stages and found that more invasive and metastatic tumours had significantly higher expression of SRSF1 showing that SRSF1 levels correlate with advanced-stage colorectal cancer." (PMID 35589755, 2022). "By pulling down SRSF1 from the CMT93 mouse colorectal cancer cells line and carrying out qRT-PCR we identified significant binding of Srsf1 to several of the alternatively spliced transcripts identified by RNAseq." (PMID 35589755, 2022). "Together, these data demonstrate that Srsf1 depletion reduces stem cell properties and results in colorectal cancer cells adopting a more differentiated cell transcriptional phenotype." (PMID 35589755, 2022). "Our Targetscan prediction results revealed that miR-202-3p targeted SRSF1, which was further confirmed by the RNA pull-down and RIP experiments Consistently, SRSF1 has reported being activated by MALAT1 in colorectal cancer cells." (PMID 34001131, 2021). "Promotes cellular proliferation, migration, and invasion via 1) binding to SFPQ and releasing oncogene PTBP2 from SFPQ/PTBP2 complex 2) increasing expression of AKAP-9 via promoting SRPK1-catalyzed SRSF1 phosphorylation in colorectal cancer cells." (PMID 27888635, 2017). "Likewise, SRSF1 promotes EMT and cell motility in breast and pancreatic cancer and, in APC-deficient colorectal cancer murine models, SRSF1 expression correlates with CSC marker expression maintaining a stemness phenotype by promoting cellular plasticity." (PMID 36980782, 2023). "Similarly, GSK3β depletion in HT29 colorectal cancer cells led to a reduction in both SRSF1 and SRPK1 protein levels, suggesting an indirect effect of GSK3β on SRSF1 via SRPK1." (PMID 26273603, 2015). "Thus, there is a clear therapeutic window for targeting SRSF1 in colorectal cancer." (PMID 35589755, 2022). "For instance, SRSF1 is involved in the alternative splicing of solute carrier family 39 member 14 (SLC39A14, zinc transporter) through the Wnt pathway in colorectal cancer cells." (PMID 36062189, 2022). "Using a RAC1 minigene in HT29 colorectal cancer (CRC) cells, Gonçalves and coworkers found that the splicing factor SRSF3 (formerly SRp20) increased skipping of alternative exon 3b, whereas another splicing factor, SRSF1 (formerly ASF/SF2), increased its inclusion." (PMID 30621237, 2019).
pancreatic cancer (14 papers, 2012 to 2025). "The following is a detailed description of the association between SRSF and pancreatic cancer: SRSF1 has been demonstrated to regulate and enhance the stability of interleukin 1 receptor type 1 (IL1R1) mRNA via alternative splicing, which increases IL1R1-L expression." (PMID 40129567, 2025). "Splicing factors (SRSF1, EIF3B, TIA1) are implicated in the enrichment of pancreatic cancer-derived exosomal miRNA, particularly contributing to the exosome shuttling of miR-1246." (PMID 38419074, 2024). "Serine/arginine-rich splicing factor 1 (SRSF1) can recognize and bind to the specific motif of miR-1246 to make it highly enriched in the exosomes derived from cancer cells, especially pancreatic cancer cells." (PMID 38203424, 2023). "A recent study confirmed that SRSF1 binds to miR-1246 (the most abundant miRNA in exosomes derived from pancreatic cancer cells) and analyzed the RNA sequences of the miRNAs highly enriched in cancer exosomes and regulated by SRSF1." (PMID 35629824, 2022). "SRSF1 was also found to confer resistance to gemcitabine in pancreatic cancer cells through promoting alternative splicing of MKN2 into the MNK2b transcript variant." (PMID 34065983, 2021). "Silencing SRSF1 restored splicing of MNK2 to the canonical MNK2a variant, led to decreased phosphorylation of eIF4E and increased the sensitivity of pancreatic cancer cells to gemcitabine treatment." (PMID 34065983, 2021). "Lentivirus shRNA knockdown of SRSF1 in pancreatic cancer cells selectively reduced exosome miRNA enrichment whereas GFP-SRSF1 overexpression enhanced the enrichment as analyzed by next generation small RNA sequencing and qRT-PCR." (PMID 32819370, 2020). "The most significant finding from the present study is that we have identified SRSF1 as a mediator of exosome miRNA enrichment in pancreatic cancer cells." (PMID 32819370, 2020). "We found that SRSF1, a recently claimed oncoprotein, is predominantly involved in regulating exosome miRNA enrichment in pancreatic cancer model systems." (PMID 32819370, 2020). "In the present study, we have provided several lines of evidence demonstrating that SRSF1, a vital splicing factor and established oncoprotein, is significantly involved in exosome miRNA enrichment in pancreatic cancer cells." (PMID 32819370, 2020). "We conclude that SRSF1 mediates selective exosome miRNA enrichment in pancreatic cancer cells by binding to a commonly shared miRNA sequence motif." (PMID 32819370, 2020). "Using a labeled miR-1246 probe as “bait”, we fished out several RBPs from pancreatic cancer cells, including serine and arginine rich splicing factor 1 (SRSF1), eukaryotic translation initiation factor 3 subunit B (eIF3B), and T cell-restricted intracellular antigen 1 (TIA1)." (PMID 32819370, 2020). "The identification of SRSF1 involvement in exosome miRNA enrichment in pancreatic cancer cells further supports the notion that the cellular exosome miRNA sorting process in eukaryotic cells may differ among different cell types." (PMID 32819370, 2020). "Serine/arginine-rich splicing factor 1 (SRSF1), as a representative, is upregulated in breast, colon, lung, and pancreatic cancer and uniformly promotes tumor progression." (PMID 39550559, 2024). "A two-stage case-control study was conducted to examine the association between six candidate U2-depedent spliceosome genes (SRSF1, SRSF2, SF3A1, SF3B1, SF1 and PRPF40B) and pancreatic cancer (PC)." (PMID 26498691, 2015). "Upregulation of SRSF1 and SRSF2 proteins has been shown in a large variety of carcinoma, including renal, breast, ovarian, cervical, colon and pancreatic cancers." (PMID 23071587, 2012). "When MYC signaling is hyperactive, it can remove this negative feedback inhibition, resulting in increasing SRSF1 expression and further speeding up pancreatic cancer." (PMID 40129567, 2025).
pancreatic cancer (continued). "Serine and arginine-rich splicing factor 1 (SRSF1) and heterogeneous nuclear ribonucleoprotein K (hnRNPK) were aberrantly upregulated in pancreatic cancer, leading to the increased expression of anti-apoptotic splice variants of Bcl-x and Mcl-1, significantly affected responses to chemotherapy." (PMID 31552163, 2019).
non-small cell lung carcinoma (11 papers, 2010 to 2025). A group of at least three distinct histological types of lung cancer, including non-small cell squamous cell carcinoma, adenocarcinoma, and large cell carcinoma. "Circ_0001786 facilitates gefitinib resistance and malignant progression in non-small cell lung cancer via miR-34b-5p/SRSF1." (PMID 40176901, 2025). "Down-regulating SRSF1 in non-small cell lung cancer cell lines can promote the occurrence of apoptosis, which is related to the down-regulation of anti-apoptotic protein survivin." (PMID 32760211, 2020). "The analysis of clinical tumor samples further confirms that there is a positive correlation between SRSF1 and survivin in non-small cell lung cancer." (PMID 32760211, 2020). "SRSF1 promotes the inclusion of the exon cassette contributing to the generation of caspase-9a proapoptotic isoform in non-small cell lung cancer (NSCLC) cells." (PMID 26273627, 2015). "In 2010, the anti-apoptotic protein Survivin was identified as the first translational oncogenic target of SRSF1 in non-small cell lung cancer." (PMID 23592547, 2013). "Analysis of The Cancer Genome Atlas (TCGA) data revealed elevated SRSF1 mRNA levels across numerous human cancer types, including those that have been largely resistant to checkpoint blockade therapies, such as melanoma and non-small cell lung cancer." (PMID 39837814, 2025). "For example, SRSF1 is highly expressed in non-small cell lung cancer." (PMID 32760211, 2020). "Subsequently, SRSF1 was found to enhance the expression of anti-apoptotic protein Survivin partially via mTOR pathway-dependent mechanism and thus promote tumorigenesis in non-small cell lung cancer." (PMID 23592547, 2013). "A recent study has revealed that RNA-binding protein SRSF1 promote tumor cell proliferation and progression by increasing LIG1 mRNA stability in non-small cell lung cancer." (PMID 32071816, 2020). "Immunohistochemical analysis of SRSF1 and SRSF2 proteins expression in non-small cell lung cancer according to histological subtype." (PMID 23071587, 2012).
liver cancer (10 papers, 2015 to 2026). An epithelial or non-epithelial malignant neoplasm that arises from the liver. "The metastasis-associated lung adenocarcinoma transcript 1 (Malat1) is over-expressed in several disease states and YAP was found to upregulate Malat1 in liver cancer, whereas SRSF1 was found to have an opposing effect." (PMID 29534050, 2018). "YAP1 up-regulates MALAT1 expression in liver cancer, whereas serine/arginine-rich splicing factor 1 (SRSF1) played an opposing role." (PMID 27835600, 2016). "Importantly, SRSF1-depleted human liver cancer cells recapitulate this pathogenesis, illustrating a conserved and fundamental role for SRSF1 in preserving genome integrity and tissue homeostasis." (PMID 36759613, 2023). "Importantly, the transient knockdown of SRSF1 in human liver cancer cells recapitulates the molecular pathogenesis identified in the animal models." (PMID 36759613, 2023). "Compared with the normal group, the expression of SRSF1, SRSF11 was found to significantly increase in the primary tumor of liver cancer." (PMID 34011971, 2021). "Whether this interaction between SRSF1 and YAP remains under normal physiological conditions remains to be seen, but the authors speculate that disrupting the interaction between SRSF1 and YAP may be a viable therapeutic target to modulate the Hippo pathway in the context of liver cancer." (PMID 29534050, 2018).